FGFR2 (fibroblast growth factor receptor 2)
Diseases named in the same sentence as FGFR2 in open-access papers (continued):
Sharing a sentence is not in itself a finding about the gene and the disease.
Cirrhosis (4 papers, 2012 to 2022). A chronic disorder of the liver in which liver tissue becomes scarred and is partially replaced by regenerative nodules and fibrotic tissue resulting in loss of liver function. "Our study revealed that FGFR2 expression may play a critical role in the progression of HCV-induced cirrhosis patients." (PMID 35683481, 2022). "Additionally, FGFR2 showed a strong positive association with HCV (p < 0.003), cirrhosis (p < 0.016), and age ≤ 50 (p < 0.012)." (PMID 35683481, 2022). "A strong correlation of FGFR2 expression was also observed in patients with cirrhosis (p < 0.0001)." (PMID 35683481, 2022). "Interestingly, a strong correlation of FGFR2 expression was observed between cirrhosis and HCV in all four HCC cohorts." (PMID 35683481, 2022). "In our study, an overexpression of FGFR2 was noted in HCV+ cirrhosis patients." (PMID 35683481, 2022). "FGF7 and FGFR2, however, were over-expressed in both cirrhosis and HCC." (PMID 23667740, 2012). "Interestingly, a recent study showed that the rs2981582 variant of FGFR2 was linked to hepato-carcinogenesis in patients with chronic HCV, suggesting that it may act as a potential biomarker for HCV-induced cirrhosis patients." (PMID 35683481, 2022). "The investigated variables were sex, cirrhosis, AFP, modified UICC stage, E-S grade, vascular invasion, and expression levels of FGFR2, VEGF, TRAIL-R1, and TRAIL-R2." (PMID 31940413, 2020). "BMP2, BMPR1A, FGF7, FGFR2 and ID3 were more highly expressed in cirrhosis than HCC, while the BMP inhibitors were more highly expressed in tumors." (PMID 23667740, 2012). "The clinicopathological analyses were performed for FGFR1, FGFR2, FGFR3 and FGFR4 against age, sex, grade stages, tumor stages, HCV, AFP, cirrhosis, vascular invasion, and cell type (atypical, dysplastic/polygonal, neoplastic) using different statistical approaches." (PMID 35683481, 2022). "Moreover, FGFR3 and FGFR4 showed a significant upregulation in advanced stages of HCC patients.The results from three independent cohorts suggested a strong positive correlation between FGFR2 expression and HCV-positive cirrhosis patients as well as HCV-positive HCC patients." (PMID 35683481, 2022). "Interestingly, a consistent pattern of FGFR1 and FGFR2 was observed in HCV-induced HCC cases, with a downregulation in FGFR1 (p < 0.028) and an upregulation of FGFR2 (p < 0.006) and cirrhosis (p < 0.02)." (PMID 35683481, 2022). "Among these genes, altered methylation of Fibroblast growth factor receptor 2 (FGFR2) and Caspase 1 (CASP1), which are involved in epithelial to mesenchymal transition, inflammation and fibrotic processes, seemed to play a crucial role in the progression to cirrhosis and HCC." (PMID 32340286, 2020).
endometrial tumors (4 papers, 2012 to 2023). "Based on our understanding of receptor tyrosine kinase-MAPK signaling, and our preliminary analysis of 115 endometrial tumors, we anticipated that FGFR2 and KRAS mutations would occur in a mutually exclusive pattern." (PMID 22383975, 2012). "Namely, while survival analysis and immunohistochemistry are both consistent with literature data suggesting EMX2 as endometrial tumor suppressor, the EMX2high group of patients were found to have higher expression of CTNNB1 and FGFR2, two known oncogenes implicated in endometrial oncogenesis." (PMID 35361846, 2022).
GEJ adenocarcinoma (4 papers, 2016 to 2025). "In our first case (46-year-old male with GEJ adenocarcinoma), molecular testing of both tissue and ctDNA identified FGFR2 amplification (plasma copy number 83.1) and a WDR11-AS1–FGFR2 fusion (2.4% VAF) was seen on ctDNA testing at disease progression." (PMID 41357601, 2025). "Additionally, in advanced G/GEJ adenocarcinoma, clinical trials of fibroblast growth factor receptor 2 (FGFR2)-targeted antibodies are underway, and FGFR2b may also become one of the future treatment targets and biomarkers." (PMID 38136288, 2023).
inflammatory bowel disease (4 papers, 2021 to 2024). A spectrum of small and large bowel inflammatory diseases of unknown etiology. "Of note, a strong reduction of FGFR2 expression was also observed in the inflamed gut of patients with inflammatory bowel disease." (PMID 39340759, 2024).
Insulin resistance (4 papers, 2015 to 2020). Increased resistance towards insulin, that is, diminished effectiveness of insulin in reducing blood glucose levels. "White pitaya juice and purified peel betacyanins (PPBNs) improved insulin resistance through decreasing fibroblast growth factor-21 (FGF-21) expression and increasing level of FGF-21 related genes (Klb, FGFR2, Egr1 and cFos) in the liver." (PMID 28886195, 2017).
Intellectual disability (4 papers, 2015 to 2023). "Patients with monoallelic WDR11 and FGFR2 deletions located in 10q26.12q26.2 were predisposed to craniofacial dysmorphisms, growth retardation, intellectual disability and cardiac diseases." (PMID 34256807, 2021).
meningioma (4 papers, 2022 to 2025). A generally slow growing tumor attached to the dura mater. "Variants typical for angiomatous (brain) meningioma are PIK3CA, KIT, PTPN11, CDH1, SMAD4, and SMARCB1; the variants typical for psammomatous meningioma are APC, FGFR2, HNF1A, STK11, and JAK3." (PMID 38476782, 2024). "The macrophages in meningioma had one drug-target kinase that was significantly increased in expression compared to VS (FLT3), whereas VS had two drug-target kinases, FGFR2 and FGFR3." (PMID 41437121, 2025). "Importantly, FGFR2 and FGFR3 were detected in meningiomas, and FGF1 was shown to be able to stimulate meningioma cell proliferation by activation of AKT1 and STAT3." (PMID 35996584, 2022).
Muenke syndrome (4 papers, 2015 to 2025). Muenke syndrome is a syndromic craniosynostosis with significant phenotypic variability, usually characterized by coronal synostosis, midfacial retrusion, strabismus, hearing loss and developmental delay. "Specific missense substitutions in this linker region in FGFR1, FGFR2, and FGFR3 cause Pfeiffer, Apert, and Muenke syndromes, respectively." (PMID 40259859, 2025).
neuroblastoma (4 papers, 2013 to 2025). Neuroblastoma (NB) is the most common solid, extracranial childhood tumor. "Elevated levels of phosphopeptides from FGFR1 and FGFR2 were also observed at high levels in these neuroblastoma cells and are implicated in the tumorigenesis of many human cancers, including neuroblastoma." (PMID 24349301, 2013). "For instance, 4-HPR inhibited EC growth by targeting VEGFR2 and FGFR2 and thereby prevented neuroblastoma biopsy-induced angiogenesis in the chick chorioallantoic membrane." (PMID 38249515, 2023). "Very little is known regarding the function of FGFR2 in neuroblastoma." (PMID 34716856, 2022). "Phosphopeptides from several RTK’s that are known for their oncogenic roles in other human tumors were identified in this neuroblastoma cell line, including IGF-1R/IR, FGFR1, FGFR2, Ret, and DDR2." (PMID 24349301, 2013). "While the role of FGFR2 in neuroblastoma drug resistance and pathogenesis remains to be clarified, our analysis, combined with its function downstream of MYCN, suggests FGFR2 may be an effective target for highly potent small molecule inhibitors." (PMID 34716856, 2022).
nevus comedonicus (4 papers, 2017 to 2025). "Genetic mosaicism due to mutations in fibroblast growth factor receptor 2, or FGFR2, have been implicated in nevus comedonicus." (PMID 38510838, 2024). "Mutations in the fibroblast growth factor-receptor gene 2 (FGFR2) gene have been implicated in numerous diseases, including nevus comedonicus (NC) and naevoid acne that have somatic missense mutations in FGFR2 in the affected tissue." (PMID 28293556, 2017).
perihilar cholangiocarcinoma (4 papers, 2022 to 2025). "In a multicenter study in Japan (PRELUDE study), we analyzed 423 patients with advanced BTC using the break-apart FISH method and found that 7.7% of iCCA and 4.8% of perihilar cholangiocarcinoma (PCC) cases were positive for the FGFR2 fusion gene." (PMID 40565050, 2025).
rhabdoid tumor (4 papers, 2013 to 2024). An aggressive malignant embryonal neoplasm usually occurring during childhood. "Other targets that have been proposed include dual blockade of tyrosine kinase receptors; PDGF-Rα/β and FGFR-2, which have been shown to be co-activated in rhabdoid tumors and can be targeted by the tyrosine kinase inhibitor (TKI), Ponatinib." (PMID 39125735, 2024). "To follow up on some of the observations made in the previous section, we measured the phosphoproteome of the FGFR2-overexpressing and FGFR2 inhibitor-sensitive rhabdoid sarcoma line G401 in response to Infigratinib in a time-dependent fashion." (PMID 38177929, 2024). "For this purpose we interrogated SNF5, FGFR1 and FGFR2 mRNA expression in a total of 991 human primary soft tissue sarcomas from publically available Affymetrix datasets and including 10 rhabdoid tumors." (PMID 24204904, 2013). "It differentially regulated EGFR, FGFR1 and FGFR2, leading to downregulation of EGFR in epithelioid sarcoma and to mesenchymal-to-epithelial transition whereas in rhabdoid tumor cells, EGFR was strongly upregulated and reinforced the mesenchymal phenotype." (PMID 34281526, 2021). "Furthermore, we did not observe increased expression levels of FGFR1 or FGFR2 in the atypical teratoid/rhabdoid tumor (AT/RT) cell line BT16 (data not shown), indicating that the correlation of SNF5-deficiency and elevated expression of FGFRs might be true only for non-CNS rhabdoid tumors." (PMID 24204904, 2013).
viral infection (4 papers, 2015 to 2024). "The implication of FGFR2 expression in HCC inducing viral infection can be studied against the therapeutic targets of HCC." (PMID 35683481, 2022). "Both that report and our study suggest a possible association with a background of continuous damage to hepatocytes, such as those related to virus infection and the presence of FGFR2 rearrangements." (PMID 33106918, 2021).
adenoid cystic carcinoma (3 papers, 2017 to 2025). A malignant tumor arising from the epithelial cells. "For example, TNBCs that present themselves as adenoid cystic carcinomas (AdCC), are genetically similar to AdCC of salivary glands, and involve several genes somatic mutations, including genes that encode fibroblast growth factor receptor 2 (FGFR2)." (PMID 28445140, 2017). "Activating FGFR2 mutations, but not the p.C382R variant, are also reported in a subset of fusion-negative adenoid cystic carcinoma." (PMID 40906279, 2025). "Whether the FGFR2-mutant group of congenital salivary gland tumors constitutes a unique entity or represents congenital/infantile presentation of an established salivary gland malignancy (such as adenoid cystic carcinoma) may also need to be addressed." (PMID 40906279, 2025).
adenoma (3 papers, 2007 to 2017). A neoplasm arising from the epithelium. "The current results showed mixed cell cultures obtained from complex carcinomas presented the highest expression levels of FGFR2, while the complex adenoma sample presented the lowest expression level." (PMID 28945747, 2017). "Such analysis provided the confirmation of FGFR-2 expression trend in thyroid samples (0.89 fold in hyperplastic tissue, P = 0.07; 0.07 fold in adenoma samples, P<0.01; 0.24 fold in carcinoma samples, P<0.01)." (PMID 23977259, 2013). "Analysis software confirmed a drastic reduction in FGFR-2-IIIb staining intensity in adenoma (15.7±4.8), corresponding to grade 0 (P<0.01 vs normal tissue)." (PMID 23977259, 2013). "As concerning FGFR-2-IIIb, in hyperplastic thyroid samples we did not observe a significant decrease with respect to normal tissue (0.87 fold, P = 0.14), while both adenoma and carcinoma samples showed a consistent reduction of FGFR-2-IIIb expression (0.13 and 0.27 fold, respectively, P<0.01)." (PMID 23977259, 2013). "In fact, both FGFR-2-IIIb and FGFR-2-IIIc transcript levels, while strongly down-modulated in adenoma and carcinoma, were virtually unchanged in hyperplasia with respect to normal tissue." (PMID 23977259, 2013). "Similar results were obtained for FGFR-2-IIIc, with no variation in mRNA expression for hyperplastic tissue (0.99 fold, P = 0.94) and strong decrease in adenoma (0.08 fold, P<0.01) and carcinoma (0.26 fold, P<0.01) samples." (PMID 23977259, 2013).
adrenal hypoplasia (3 papers, 2013 to 2025). "FGFR2 is expressed in the outer cortex of mouse and human adrenal glands and FGFR2 loss during fetal life leads to adrenal hypoplasia, but the precise role FGFR2 plays during postnatal adrenal morphogenesis and maintenance of mature zG cell identity in the adult remained poorly understood." (PMID 40956622, 2025). "The global Fgfr2-IIIb knockout results in embryonic lethality due to severe malformations, including adrenal hypoplasia." (PMID 28386245, 2017). "Additionally, engineered deletion of the FGF ligand, FGF2 or the FGF receptor Fgfr2, results in various degrees of adrenal hypoplasia after birth." (PMID 28386245, 2017). "Conditional deletion of both isoforms of Fgfr2 from steroidogenic tissue also leads to adrenal hypoplasia and global hemizygous deletion of exon IIIc of Fgfr2 does not appear to have any gross effect on adrenal development, unlike on the development of other visceral organs." (PMID 23376610, 2013).
adrenocortical carcinoma (3 papers, 2017 to 2023). "In this context, we asked whether FGFR2-expression is also present in adrenocortical carcinomas and if it is associated with the mutational status of CTNNB1 and clinical characteristics." (PMID 32522271, 2020). "The study was designed as a pilot study to identify FGFR2 as a potential target for further investigations in adrenocortical carcinoma." (PMID 32522271, 2020). "Paraffin embedded tissue specimens of adrenocortical carcinoma were examined by immunohistochemistry technique using an affinity purified polyclonal antibody raised against the c-terminal cytoplasmatic domain of the FGFR2." (PMID 32522271, 2020). "Therefore, further experiments might concentrate on the differential expression and intracellular localization of FGFR2 isoforms in adrenocortical cancer cells." (PMID 38269250, 2023). "Our study does not allow a precise quantitative analysis of FGFR2 expression in adrenocortical carcinomas but provides a qualitative first insight." (PMID 32522271, 2020). "Therefore we hypothesised that FGFR2 expression may also play a role in adrenocortical carcinoma (ACC)." (PMID 32522271, 2020). "In these seven patients, three PRs (two with FGFR2 fusion-positive iCCA and one with urothelial cancer with FGFR2 and FGF19 amplification) and two durable SDs with tumour reduction (FGFR2 fusion-positive iCCA and adrenocortical carcinoma with FGFR1 amplification) were observed." (PMID 28972963, 2017).
bladder urothelial carcinoma (3 papers, 2021 to 2023). "Frequent activating mutations of FGFR2 are discovered in 10% of bladder urothelial carcinomas (BLCAs) and UCECs." (PMID 33968743, 2021). "Erdafitinib, type I1/2A pan-FGFR inhibitor, is FDA-approved for treating locally-advanced, unresectable, or metastatic urothelial carcinoma that has progressed during or after platinum-based chemotherapy and as first-line treatment of urothelial bladder cancer exhibiting FGFR2 or 3 mutations." (PMID 37681152, 2023). "Furthermore, ICP-192 is evaluated in a phase II study (NCT04492293) recruiting patients with bladder urothelial cancer harboring FGFR2 genomic aberrations." (PMID 37681152, 2023).
Diabetic Foot Ulcer (3 papers, 2025 to 2026). "Fig7B and 7C displays the expression levels of CCL20, CXCL13, FGFR2, FGFR3, PI3, PLA2G2A, and S100A8 across the six cell types.The results showed that the key pathogenic genes of diabetic foot ulcer were mainly involved in keratinocytes and neutrophils." (PMID 40749079, 2025).
emphysema (3 papers, 2005 to 2022). "Pharmacologic modulation of Fgfr2 signaling could be used to support alveolar health during acute injuries like these, helping sustain AT2 cells as a virus or toxin destroys them, and perhaps similarly in chronic diseases such as COPD/emphysema and pulmonary fibrosis." (PMID 36414616, 2022).
endometrial endometrioid adenocarcinoma (3 papers, 2015 to 2024). A primary endometrial adenocarcinoma composed of neoplastic cells that form complex glandular patterns associated with budding and branching of the neoplastic glands. "As the variant p.(Asn549Lys) in FGFR2 has previously been linked to an endometrial endometrioid adenocarcinoma, we hypothesize that the presented mosaic FGFR2-associated neurocutaneous syndrome is associated with an increased tumor risk, although further cases are needed to verify this." (PMID 38265560, 2024).
hepatitis B (3 papers, 2021 to 2025). "Smoking, alcohol consumption, and hepatitis B virus infection have all been reported as potential risk factors associated with FGFR2 fusion-positive iCCA." (PMID 40565050, 2025).
Hyperglycemia (3 papers, 2016 to 2021). An increased concentration of glucose in the blood. "Despite reduced adiposity, treatment with FGFR2-IIIc antibody did not suppress hyperglycemia induced by social isolation in KKAy mice." (PMID 27892934, 2016). "In summary, these findings suggest that the treatment with FGFR2-IIIc antibody suppresses body weight gain and adiposity without affecting food intake and hyperglycemia in individually housed KKAy mice." (PMID 27892934, 2016).
invasive ductal carcinoma (3 papers, 2020 to 2025). "While FGFR2’s role in endocrine resistance is established, its potential involvement in shaping immune infiltration—particularly in the transition from ductal carcinoma in situ (DCIS) to invasive ductal carcinoma (IDC)—remains underexplored." (PMID 41018083, 2025). "Out of 2509 BCa patients from the METABRIC-TCGA database, 1242 fulfilled the requirements of the study, i.e., invasive ductal carcinoma of no special type (IDC, NST), available data on follow-up, FGFR2 gene mRNA, and hormonal receptor status, and were selected for the analysis." (PMID 32971804, 2020).